TNF (tumor necrosis factor)
Diseases named in the same sentence as TNF in open-access papers (continued):
Sharing a sentence is not in itself a finding about the gene and the disease.
tumor (continued). "The results showed a remarkable increase in the tumor tissue level of pro-inflammatory TNF-α in the Ehrlich group, representing 1150% change from the normal control group." (PMID 35798765, 2022). "Generally, circulating lymphocytes modulate tumor growth and improve the survival rates of cancer patients through the production of cytokines (IFN-γ and TNF-α), and thus reduced quantity or exhaustion of lymphocytes impairs immune surveillance and defense in cancer." (PMID 36338698, 2022). "Furthermore, the iNK cells can produce IFN-γ and TNF-α in the presence of PMA/ionomycin, K562 tumor cells, or IL-2." (PMID 36344493, 2022). "N1 neutrophils can exert anti-tumor functions through an antibody-dependent cellular cytotoxicity (ADCC) effect, producing radical oxygen species (ROS), TNF-α, and nitric oxide with a direct killing effect, and inhibiting suppressive cells, such as IL-17-producing γδ T lymphocytes." (PMID 36294305, 2022). "TNF-α exhibited its protumorigenic features through activation of representative c-Jun N-terminal kinase (JNK) and NF-κB signaling pathways, resulting in enhanced epithelial to mesenchymal transition (EMT) and accelerated tumor cell invasion." (PMID 35309351, 2022). "KD reduces the production of pro-inflammatory cytokines, including tumor necrosis factor-α (TNF-α), interleukin-1β (IL-1β), interferon-γ (IFN-γ), and cyclo-oxygenase 2 (COX-2), which are involved in tumor growth, proliferation, angiogenesis, invasion, metastasis, and DNA damage." (PMID 36139562, 2022). "Further analysis showed that the contents of IL-10 and TGF-β was significantly increased in tumor tissues, but there were no significant changes of TNF-α, IL-6, and IL-1β observed compared with the control group." (PMID 35646112, 2022). "In addition, tumor cells, including GBM, are known for their dysregulated signaling and epigenetic regulation, potentially resulting in TNF-α-independent MCP-1 release." (PMID 35159079, 2022). "It was confirmed that CD47 upregulation in refractory lung tumor models was mediated by the TNF-α/NF-κB1 signaling pathway, and blocking CD47 could enhance anti-tumor effects." (PMID 36523419, 2022). "KOMAP, a polysaccharide from P. eryngii, significantly increased the immune organ index, LPS- or ConA-induced splenocyte proliferation, serum levels of cytokines including IL-2, TNF-α and IFN-γ, as well as the activity of NK and CTL cells in tumor-bearing mice." (PMID 35585984, 2022). "High TNF and interleukin-6 (IL-6) levels, which are known to be responsible for the proliferation and metastatic potential of tumor cells, indicate a negative prognosis for the patient." (PMID 35740575, 2022). "NAMPT expression can be regulated by different inflammatory signals in several types of tumor and immune cells, and, in turn, eNAMPT increases the levels and the release of pro-inflammatory cytokines IL6, IL10, IL1β, and tumor-necrosis factor-α (TNF-α) from leucocytes." (PMID 36077374, 2022). "In this study, we showed that N. caninum injection increased infiltration of CD8+ T cells and macrophages into the tumor, along with increased expression of IL-12, IFN-γ, IL-10, TNF-α, and IL-2 mRNA, which can also be induced by N. caninum in a mouse model, as reported in other studies." (PMID 36138417, 2022). "Furthermore, TNF-α, VEGFA, and c-Myc were considered to serve important roles in tumorigenesis and tumor development, which can be regulated by HDAC1." (PMID 35053925, 2022). "The increased expression of proinflammatory cytokines (IL-6, TNFα, IL-1B) found here in the aggressive PCa-related PPAT supports the role of PPAT in aggravating the tumor microenvironment, either by direct effects on premalignant cells or by acting on the tumor microenvironment." (PMID 35978404, 2022).
tumor (continued). "We also observed the enrichment of several immunological signatures, such as “TNFα/NFκB signaling” and “immune cells”, which was consistent with the immune infiltration findings, suggesting that KRAS may affect the anti-tumor immune response." (PMID 35563733, 2022). "Activated M1 macrophages typically express CD40 and CD86 and secrete higher levels of proinflammatory factors than M2 macrophages, such as IL-1α, tumor necrosis factor (TNF), and IL-12, which mainly exert an antitumor immune response and directly kill tumor cells in the early stage of a tumor." (PMID 35740975, 2022). "The highest proportions of cells producing IFN-γ and/or TNF-α in response to tumor Ag stimulation were found in cultures expanded from the CD39+ memory Tconv subpopulation, indicating that it was enriched in patients in tumor-Ag-specific T cells." (PMID 35954341, 2022). "Inhibition of γ‐secretase in tumor cells reduced sFn14 secretion, increased full‐length Fn14 at the cell surface, and enhanced TWEAK ligand‐stimulated Fn14 signaling through the NFκB pathway, which led to enhanced release of the cytokine tumor necrosis factor." (PMID 36069059, 2022). "Since apoptotic tumour cell-CM per se does not affect macrophage TNFα release, this effect is likely mediated by neutrophils which are attracted towards apoptotic tumour cell-derived factors." (PMID 35121727, 2022). "Some of the mediators that are recognized include tumor necrosis factor (TNF), vascular endothelial growth factor (VEGF), interleukin-6 (IL6), which has a key role as a growth factor for tumor cells, hepatocyte growth factor (HGF), and transforming growth factor beta (TGF-β)." (PMID 36362398, 2022). "Those tumor-infiltrating pDCs are poor IFN-I producers, because of cytokine dysregulation by transforming growth factor β (TGF-β) and TNF-α secretions in the tumor microenvironment that inhibit the IFN-I secretion of pDCs through the inhibition of IRF-7 expression, and favors Treg expansion." (PMID 35884612, 2022). "To investigate whether the expression of LINC01123, B7–H3, or miR-214-3p in HNSCC cells affects CD8+T-cell function, we analyzed the expression of TNF-α, IFN-γ, perforin, and granzyme B in the CD8+T cells by flow cytometry after coculture with the tumor cells." (PMID 35115487, 2022). "When tumor necrosis factor (TNF)-related apoptosis-inducing ligand (TRAIL) was discovered in 1995, many studies were performed to demonstrate that it selectively induces apoptosis in tumor cells in vivo." (PMID 35428370, 2022). "M2 TAMs secrete pro-tumor factors (such as IL-4, IL-6, IL-10, IL-13, EGF, and VEGF), while the tumor suppressor M1 TAMs expresses anti-tumor factors (such as IL-12, the major histocompatibility complex (MHC) class II, and TNF-α)." (PMID 36358823, 2022). "Previous studies of tumor-induced osteoclastogenesis can be divided into those focusing on the generation of RANKL by tumor cells, the generation of effectors of RANKL-induced osteoclastogenesis, and the generation of TNF-α, which alone induces osteoclasts." (PMID 36614130, 2022). "However, consistent with the TDM-1 experiments, tumours treated with U3-1402 exhibited higher levels of pro-inflammatory cytokines such as IFN-γ, TNF-α, and IL-2, and in vivo depletion of CD8+ cells reduced its anti-tumour efficacy." (PMID 36046842, 2022). "It is worthwhile noting that a large panel of cytokines including MCP-1, M-CSF (CSF-1), IL-3, IL-10, IL-12, IL-16, MIP-1β, RANTES, TNF-α and TGF-β2 were upregulated resulting from autocrine effect in POSTN-overexpressing SKOV3 cells leading to potent enrichment of TAMs in the tumor microenvironment." (PMID 36550569, 2022). "Frequencies of CD8+IFN-γ+ and CD8+IFN-γ+ TNF-α+ T cells showed negative relationship with tumor grade (P = 0.035 and P = 0.043, respectively)." (PMID 36376825, 2022).
tumor (continued). "In addition, we found a modestly increased secretion of cytokines and chemokines (e.g., IL-6, TNF-α, MIP-1) by macrophages with the combination therapy compared with monotherapy, likely a result of their enhanced ADCP of tumor cells." (PMID 35167491, 2022). "The increased expression of TNF-α, TGF-β, MMP-2, and MMP-9 might explain how the P. gingivalis LPS exerts pro-tumor effects." (PMID 36552854, 2022). "Administering Lactiplantibacillus plantatum LS/07 repressed the tumor frequency, accompanied by an increase in CD4+ T-cells in tumor tissue, reduction in the serum tumor necrosis factor-α concentration, and elevation in CD8+ T-cell number in tumor tissue but decreased blood CD8+ T-cell count." (PMID 36615662, 2022). "Among tumor clusters, the difference in chemoresistance-related expression was major in stemness-related expression, including EMT, Notch, TNFα, Hedgehog, and BMP gene sets, when the ABC transporter, DNA repair, TGFβ, Wnt β-catenin and MAPK gene set scores were relatively uniform." (PMID 35664733, 2022). "Finally, pentoxifylline and thalidomide, inhibitors of tumor necrosis factor (TNF)-α synthesis, enhanced the anti-tumor action of anti-cancer drugs." (PMID 35408786, 2022). "Conversely, ligand IFNG and its related pro­inflammatory cytokine TNF, and ligands related to tumor necrosis factor family and cytotoxicity were expressed in CD8+ T cells, indicating the killing potential of CD8+ T cells against tumor cells." (PMID 35903095, 2022). "However, Mono-FCGR3A in high tumor infiltration group expressed lower levels of MHC molecules, inflammatory cytokines and chemokines (HLA-DRB1/HLA-DPB1, TNF, IL1B, CCL3 and CCL4), which meant the sub-cluster was less involved in immune responses." (PMID 36532059, 2022). "Importantly, a combination treatment of ATRA and anti-PD-L1 antibody further delayed U14 tumor growth and increased the proportion of CD62L−CD8+ T cells, CD62L−CD4+ T cells, CD107a+CD8+ T cells as well as IFN-γ and TNF-α levels in tumors." (PMID 35688951, 2022). "In addition, TNF-α and VEGF secreted by activated mature PPAT adipocytes facilitate PPAT lipoblasts seeding to the PCa tumor stromal microenvironment, thus promoting PCa progression by inducing vascularity and increasing vascular permeability." (PMID 35406450, 2022). "Moreover, Ruxo increased TNF, IFN-γ, perforin, and IL-2 production by CD4+ TILs, essential effector molecules in anti-tumor immunity; similar increases of IFN-γ, perforin, and GzmB were also noticed in CD8+ TILs." (PMID 36008408, 2022). "Consequently, anti-tumor effector molecules, such as IL2, IFNγ, TNFα, and granzyme B (GZMB), is dramatically downregulated in the CTLs and NK cells, and immune exhaustion and dysfunction are provoked locally and systemically in the host." (PMID 36211375, 2022). "However, the overexpression of CD36 induces LPO and triggers the ferroptosis of CD8+ T cells, leading to a decrease in the anti-tumor effectors IFN-γ and TNF-α; this accelerates tumor progression and results in poor prognosis." (PMID 35372083, 2022). "The ability of CD8+TIGIT+ cells to secrete cytokines (TNF-α and IFN-γ) was significantly lower than that of CD8+TIGIT− cells, which indicated that CD8+TIGIT+ cells have low effector function and anti-tumor potential." (PMID 35729552, 2022). "However, macrophages undergo polarization and metabolic reprogramming when stimulated by external pathogens, cytokines, and tumor metabolism, such as LPS, IFN-γ, TNF-α, IL-1, IL-4, IL-10." (PMID 35874739, 2022). "Furthermore, the tumor levels of RANTES correlated significantly with those of PD-L1, TNF-α, TGF-β, VEGF-A, and VEGF-C." (PMID 35208526, 2022).
tumor (continued). "TGF-β and IL-10 expression decrease synthesis of IFNγ and TNF-α by pro-inflammatory CD4 T cells, and in turn reduce tumor-specific cytotoxicity of CTLs, prevent activities of dendritic cells and NK cells, and result in tolerance to tumor cells." (PMID 35372046, 2022). "In addition, we have developed a therapeutic approach to improve tumor perfusion in PNET and breast cancer models using an immune modulating cytokine tagged to CSG peptide, TNFα-CSG." (PMID 35273916, 2022). "Furthermore, the melittin–dKLA group showed a decrease in TGF-β mRNA expression and an increase in TNF-α and IFN-γ mRNA expression in tumor tissues." (PMID 35328518, 2022). "Thus, we determined tumor soluble factors that include angiogenic (VEGF), type 1 response (TNF-α, IFN-γ), type 2 response (IL-4, IL-5), and regulatory (IL-10) soluble factors." (PMID 36233245, 2022). "As TNF-a exerts its biological functions by activating distinct signaling pathways such as NF-κB, a major cell survival signal, the decreased expression of both proteins agrees with si-m/h-VDAC1-B treatment, decreasing tumor growth." (PMID 35883451, 2022). "We performed cancer immunotherapy using three different cytokine genes: interleukin 12 (IL12) and newly designed secreted isoforms of tumour necrosis factor‐α (TNFα) and interleukin 15 (IL15), as they have been shown to produce potent, cell‐mediated anti‐tumour effects." (PMID 35758207, 2022). "In addition, Cytimmune Sciences of the United States co-modified recombinant human tumor necrosis factor (rh TNF)-α and sulfhydryl PEG on the surface of gold nanoparticles, and successfully constructed a highly effective anti-tumor drug." (PMID 35664731, 2022). "ADP@SWNT/TNFα inhibits tumor growth and metastasis both in vivo and in vitro, and the anti‐tumor effect is enhanced by NIR irradiation, suggesting its high potential for application in tumor therapy." (PMID 34994069, 2022). "Tumor CD4+ T cells showed a significant reduction in number and an increased expression of programmed death-1 (PD-1), and decreased CD107a expression and cytokine such as IFN-γ and TNF-α production, indicating dysfunction." (PMID 36611881, 2022). "This bsApt also induced an immune response (infiltration of CD3+ lymphocytes at tumor with increased expression of IFNγ, TNFα, and IL-10) and potentiated a combination of GVAX and transient Foxp3 blockade via the P60 peptide (resulting in decreased tumor size and increase survival) in vivo." (PMID 35141049, 2022). "Inflammatory cells produce tumor necrosis factor α, transforming growth factor β, interleukin-6, and other cytokines, and these inflammatory agents regulate nuclear factor (NF)-κβ and the STAT3 pathway and encourage metastasis in tumor cells." (PMID 35387666, 2022). "TNF-α role within the TME is versatile and supports tumor growth in many mechanisms." (PMID 35798765, 2022). "Experience with biologic DMARDs is limited, but some cases reported satisfactory responses with IL-6 inhibitors or TNF-α inhibitors without a significant impact on tumor response." (PMID 35783644, 2022). "Additionally, JQ1 treatment with radiation and cisplatin synergistically increased the Tumour necrosis factor alpha (TNF‐α) and IFN‐γ levels, the major anti‐tumour cytokines secreted by cytotoxic T cells, in Lewis tumours." (PMID 35083874, 2022). "Anti-EpCAM CAR T-cells used against CRC cells and models exhibited cytotoxic lysis of the targeted cells that secreted cytotoxic cytokines, including IFN-γ and tumor necrosis factor-alpha (TNF-α), resulting in tumor growth and development in xenograft mouse models." (PMID 35814023, 2022). "Furthermore, TNFα signaling and IL2/STAT5 signaling pathways were also enriched in FAP+ fibroblastsHighSPP1+ macrophagesHigh tumor samples." (PMID 35365629, 2022).
tumor (continued). "TNF‐α can then stimulate the production of the macrophage chemoattractant protein 1 (MCP‐1) by both monocytes and tumour cells, and trigger the recruitment of macrophages into tumour lesions and restriction of tumour growth." (PMID 35344301, 2022). "As one of the dominant cell types in the inflamed intestine, macrophages produce various cytokines, including IL‐6, IL‐12, IL‐23, IL‐1β and TNF, which modulate IEC activity and immune responses and evolve with and provide support to tumour cells during the transition to malignancy." (PMID 35363937, 2022). "The secretion of TNF-α, IFN-γ, IL-6, and other cytokines by CD4+ T cells can change the TME, induce the local invasion of T lymphocytes into the tumor, inhibit the synthesis of DNA and RNA of tumor cells, and thus, induce the apoptosis of tumor cells." (PMID 36389763, 2022). "Combined with the observation that LINC01198’s activation in tumor cells increased IFN-γ, GzmB, and type I–related cytokine (i.e., CXCL10 and TNF-α) secretions, we hypothesized that LINC01198 regulated IFN signaling pathways in cancer cells." (PMID 36475797, 2022). "It has been reported that the main role of TNF-α in the body is not to kill tumors but rather to promote tumor development as an inflammatory factor." (PMID 36225358, 2022). "Similarly, the secretion of IL-2, IL-13, and TNF-α is significantly higher in tumour-conditioned media (TCM) derived from 1,4-dihydroxy quininib treated primary UM tumours vs. vehicle." (PMID 36698840, 2022). "Interestingly, M1-like anti-tumor macrophage-derived EVs can transport higher mRNA amounts of M1 markers, including CD86, IL-6, TNF-α and iNOS, toward M2 macrophages and further induce M2 to M1 repolarization." (PMID 35927755, 2022). "SRSF3 is closely related to tumor necrosis factor (TNF)-related ligands and receptors, suggesting that SRSF3 may play an important role in tumor immunity." (PMID 35494088, 2022). "The previous reports demonstrated that PD-L1 protects LN LECs and tumor cells from apoptosis, while we observed that loss of PD-L1 in dermal LEC increased cell viability and prevented apoptosis induced by IFNγ but not TNFα." (PMID 35449134, 2022). "Moreover, activated CTLs also secrete cytotoxic cytokines, including interferon-γ (IFN-γ) and tumor necrosis factor-α (TNF-α), to elicit cytotoxicity in tumor cells." (PMID 36189283, 2022). "This polarization was also confirmed via increasing in the expression level of cytokines such as interferon gamma (IFN-γ) and tumor necrosis factor alpha (TNF-α) which led to a significant reduction in the amount of interleukin 10 (IL-10), an immunosuppressive cytokine that promotes tumor growth." (PMID 35954362, 2022). "In addition, the cytokines (TNF-α+IFN-γ+) secretion of CD8+T cells in the tumor tissues was less than that in para-tumor tissues, indicating that the function of CD8+T cells in tumor tissues was weaker than that in para-tumor tissues." (PMID 36260222, 2022). "The binding of the receptor tyrosine kinase MET, expressed on neutrophils, by the tumor necrosis factor-alpha (TNFα), and its ligand, the Hepatocyte growth factor (HGF), drives the nitric oxide synthase (NOS) and the consequent release of the anti-tumor inflammatory mediator." (PMID 35664746, 2022). "Additionally, intracellular cytokine staining in YUMM3.3 tumor-infiltrating CTLs revealed a marked INHBA-induced decrease in IFNγ, TNFα, and GzmB protein levels." (PMID 35580932, 2022). "Immune cells that surround BE and EAC, including myeloid-derived suppressor cells, T-regulatory cells and Th17 cells, secrete proinflammatory cytokines including IL-6, IL-19, TNFα and TGF-β, resulting in a tumor permissive environment that promotes tumor cell survival, proliferation and metastasis." (PMID 35267943, 2022). "Likewise, in cervical cancer, TNF-α and TGF-β collaboratively induce EMT and tumor stem cell-like properties through the NF-kB/Twist axis." (PMID 35965509, 2022).